RNU7-188P (RNA, U7 small nuclear 188 pseudogene)
Gene: Small nuclear RNA gene on chromosome 7 (96,377,857 to 96,377,920, forward strand). Ensembl gene ENSG00000252872.
Homologues: Orthologues: chimpanzee U7 (100% identical), macaque U7 (98% identical). Paralogues in human: U7 (86% identical), RNU7-55P (84% identical), RNU7-65P (83% identical), RNU7-2P (81% identical), RNU7-52P (81% identical), RNU7-60P (81% identical), RNU7-84P (81% identical), RNU7-9P (81% identical), U7 (81% identical), RNU7-1 (80% identical), RNU7-12P (80% identical), RNU7-167P (80% identical), and 143 more.